CD36 (CD36 molecule (CD36 blood group))
Diseases named in the same sentence as CD36 in open-access papers (continued):
Sharing a sentence is not in itself a finding about the gene and the disease.
tumor (continued). "In cancer-associated fibroblasts (CAFs), CD36 regulates lipid uptake and matrix protein production to promote tumor proliferation." (PMID 36354702, 2022). "Cluster M0 highly expressed immunosuppressive and angiogenic phenotype-related markers (SLC40A1, NRP1, and CD36) and promote tumor progression associated with markers (CD163 and CD163L1)." (PMID 35265520, 2022). "Recent studies have highlighted the role of CD36 in mediating lipid uptake by tumor-associated immune cells and in promoting tumor cell progression." (PMID 36354702, 2022). "Tumor-associated macrophages (TAMs) up-regulate CD36 to uptake lipids resulting in lipid accumulation." (PMID 36106108, 2022). "As metabolic rewiring plays a role in the survival of tumor cells, different studies have implicated CD36 in carcinogenesis." (PMID 36358940, 2022). "Previous studies have highlighted that tumor-associated immune cells undergo CD36-oriented lipid metabolic reprogramming, which leads to immune evasion and cancer progression." (PMID 36203151, 2022). "Here, we found that, in vivo, tumor-derived extracellular vesicles were transferred less efficiently to macrophages that are CD36-deficient." (PMID 36184646, 2022). "CD36 is expressed in tumor cells, and CD36 deficiency is characterized by stromal tumor and high cancer risk; the lower the CD36 stromal level, the more aggressive the tumor." (PMID 36114448, 2022). "In PCa, both FA uptake and CD36 levels are upregulated in human malignant tissue, while genetic ablation of the receptor in Pten-deficient mouse models can impair tumor burden." (PMID 36358940, 2022). "Increased expression of CD36 in tumor epithelium is associated with poor prognosis of various GI carcinomas as well as of ovarian cancer, glioblastoma, oral squamous cell carcinoma, and melanoma." (PMID 35991116, 2022). "Here the authors show that CD36-expressing metastasis associated macrophages engulf tumor cell-derived extracellular vesicles enriched in long-chain fatty acids, acquiring a pro-tumorigenic phenotype in a preclinical liver metastasis model." (PMID 36184646, 2022). "In TME extracellular free fatty acids, including palmitic acid, oxLDL or oleic acid, are transported into cells via membrane-associated CD36 and promoted tumor growth and metastasis." (PMID 36686729, 2022). "High expressions of CD36 were also reported in other immunosuppressive cells, such as tumor-associated macrophages and myeloid-derived suppressor cells, and the malignancies of various human cancer types." (PMID 36275711, 2022). "MFO is actually related to a lower CD36 content or lower CS activity, intimately linked to atherosclerotic processes or tumor defense, as well as poorer physical performance." (PMID 35464093, 2022). "Numerous cancers, such as ovarian cancer, glioblastoma, human oral cancers, and breast cancer, have been linked to CD36, which promotes primary tumor growth and disease progression." (PMID 36556492, 2022). "Of note, CD36 is linked to fueling tumor metastasis and drug resistance by increasing FAO in cancer and is a potential target for cancer treatment." (PMID 33902674, 2021). "CD36 deficiency in macrophages repolarizes them to an M1-like anti-tumor TAM that can suppress growth and progression of tumors in vivo." (PMID 34988072, 2021). "Suppression of tumor growth,linked with increased pro-inflammatory cytokine expression, was also observed upon mousetreatment with a CD36-blocking antibody." (PMID 34603769, 2021). "Exogenous lipids, including PUFAs and MUFAs, absorbed via CD36 induce metabolic and functional reprogramming of tumor-associated myeloid-derived suppressor cells (MDSCs)." (PMID 33801564, 2021). "In PDAC, the decreased expression of CD36 is associated with large tumor size and reduced survival rate, and less associated with TNM staging." (PMID 32781778, 2020). "The tumor-promoting effect of CD36 is associated with an increase in the levels of pAkt and survivin." (PMID 32850342, 2020).
tumor (continued). "In the tumor stroma, CD36 expression is also deficient; the lower the CD36 level in the stroma, the more aggressive the tumor." (PMID 32781778, 2020). "In particular, CD36 was shown to mediate lipid accumulation and fatty acid oxidation in tumor-associated macrophages, resulting in a pro-tumorigenic gene expression profile." (PMID 33604295, 2020). "In the gene expression assays, the health-associated species mostly downregulated CD36, a gene that plays an important role in tumor growth and metastasis, while P. gingivalis upregulated it." (PMID 33123499, 2020). "Intraperitoneal injection of CD36-deficient cells significantly reduced the number of metastatic nodules in the abdominal of xenograft mouse tumor model." (PMID 33194756, 2020). "Ablation or neutralization of CD36 led to the loss of suppressive function and reduced tumor growth in mice, demonstrating the importance of fatty acid uptake by Tregs." (PMID 33604295, 2020). "These lines of evidence suggest that CD36 deficiency is representative of the tumor stroma and high cancer risk: the lower the CD36 level in the stroma, the more aggressive the tumor." (PMID 31410189, 2019). "We further validated these results using the TCGA database which showed that the expression level of CD36 in tumor tissues was also significantly associated with depth of local tumor invasion and higher TNM stage of GC, and also with lymph node involvement." (PMID 30717785, 2019). "Results with another mouse model of metastatic breast cancer indicated that although CD36 expression in the whole primary tumour was downregulated, this alteration was related to loss of stromal receptor." (PMID 30069479, 2018). "CD36 has also been associated with increased pro-inflammatory signalling and the production of reactive oxygen species, both known to influence tumour development." (PMID 30065793, 2018). "CD36 is significantly repressed in multiple cell types of disease-free stroma associated with high mammographic density and tumor stroma." (PMID 28186980, 2017). "Additionally, CD36 is intricately linked with the function of cancer-associated fibroblasts and the remodeling of the tumor stromal microvasculature." (PMID 41595136, 2026). "Similarly, CD36 is overexpressed in cancer cells, where it promotes changes in functions associated with tumor development and progression." (PMID 39967671, 2025). "CD36, a lipid-associated transmembrane protein involved in FAs recognition and translocation, has been linked to tumor progression via EMT in various cancers, though its role in CRC remains unclear." (PMID 40640171, 2025). "These associations suggest that CD36 may contribute to tumor progression by enhancing chemokine-mediated immune cell recruitment and inflammatory signaling." (PMID 41550652, 2025). "Furthermore, overexpression of CD36 has been linked to poor prognosis and immunosuppressive tumor microenvironments, positioning CD36 as a compelling therapeutic target with ongoing preclinical exploration using antibodies, inhibitors, and genetic models." (PMID 41550652, 2025). "Notably, tumor-associated Tregs showed significantly higher expression of CD36 than normal Tregs from the SPL and LNs." (PMID 39773913, 2025). "CD36, a lipid transporter, has also been implicated in regulating the metabolic reprogramming of neutrophils within the tumor microenvironment, where it may facilitate immune suppression." (PMID 40549016, 2025). "Furthermore, tumor cells themselves can also express CD36, which is associated with increased metastatic potential and the induction of EMT, a process that enhances cell migration and invasion." (PMID 40051496, 2025). "CD36 has been linked to promoting chemoresistance in cancer cells and inhibition of CD36 has been reported to evoke immunostimulatory effects and decreased tumour aggressiveness in-vitro." (PMID 39965288, 2025).
tumor (continued). "These associations indicate that CD36 may also promote an immunosuppressive tumor microenvironment, potentially facilitating immune evasion." (PMID 41550652, 2025). "CD36 immuno-positivity was associated with high tumor grade, stages, shorter OS, and DFS." (PMID 40060230, 2025). "In contrast, tumor-associated immune cells, such as TAMs and MDSCs, often show increased cholesterol biosynthesis and uptake through lipoprotein and scavenger receptors (e.g., CD36), along with impaired cholesterol efflux, leading to cholesterol accumulation." (PMID 40270603, 2025). "Furthermore, tumor immunological tolerance and carcinogenesis can be linked to CD36-driven lipid metabolic reprogramming and the function of tumor-associated immune cells." (PMID 38370376, 2024). "In addition, an increasing number of studies have shown that upregulated CD36 is associated with tumor progression." (PMID 38319449, 2024). "The inability of Cpt1a-deficient tumor cells to metabolize exogenous palmitate could also be attributed to a reduction in FA uptake and the expression of Cd36, an integral plasma membrane protein that imports FAs into cells and is implicated in breast cancer." (PMID 39097623, 2024). "What’s more, to verify whether CB2R enhances phagocytosis by increasing CD36 levels on tumor-associated macrophages, we treated xenografted mice with SSO, an irreversible CD36 inhibitor." (PMID 39691192, 2024). "The tumour suppressive consequences of Cd36 deletion in Pten loss-induced PCa suggest that knowledge and therapeutic strategies reported for other tumour types could be implemented in this disease." (PMID 38969865, 2024). "Therefore, CD36 regulates lipid metabolism reprogramming to promote cancer progression and functions in tumor-associated immune cells to suppress antitumor immune activity." (PMID 38319449, 2024). "CD36 deficiency in the tumor microenvironment may contribute to multiple processes critical to tumor progression, including metabolic reprogramming, inflammation, and angiogenesis." (PMID 37816052, 2023). "CD36 contributed to tumor growth and progression and was associated with PD-L1 expression." (PMID 36726488, 2023). "In addition, tumor-associated macrophages (TAMs) residing in TME accumulate lipids through enhanced lipid uptake via CD36." (PMID 38060103, 2023). "CD36 expression is associated with tumor cell growth and metastases." (PMID 36726488, 2023). "Moreover, a recent study demonstrated that the genetic ablation of Cd36 was able to abrogate the development of M2 tumor-associated macrophages (TAMs) and preferentially promote the maturation of pro-inflammatory M1 macrophages." (PMID 37371076, 2023). "Additional studies implicated the scavenger receptor CD36 as a possible mediator of increased fusion between tumor cells and monocytes/macrophages, as upregulation of CD36 in both CSCs and monocytes, induced by exposure to 4-hydroxynonenal, significantly increased hybrid formation." (PMID 37427108, 2023). "Furthermore, CD36 overexpression has been associated with faster tumor growth, cancer progression, and metastasis initiation." (PMID 37063269, 2023). "Moreover, CD36 was found to promote sterile inflammation and activate the protumor ability of tumor-associated immune cells." (PMID 36147494, 2022). "Our work suggests that targeting CD36 on MAMs helps to relieve tumor-macrophage metabolic interdependence and associated immune suppression, which may be an appealing therapeutic strategy against liver metastasis." (PMID 36184646, 2022). "Moreover, CD36 is associated with tumor invasion and metastasis and is a prognostic biomarker for various types of cancer." (PMID 36106108, 2022). "Our data so far have linked mitochondrial activity to the CD44HCD36H metastasis-initiating tumour cells, but it is unclear whether the downregulation of CD36 is a cause or a consequence of m5C- and f5C-dependent mitochondrial metabolic reprogramming." (PMID 35768510, 2022).
tumor (continued). "Increasing evidence has shown that the abnormal expression of CD36 in immunocytes may be involved in tumor-associated processes, such as tumor angiogenesis and tumor immune evasion." (PMID 36131916, 2022). "In addition to increase immune checkpoints in CD8+ T cells, cholesterol-rich TME promotes CD36 over-expression, which is associated with tumor progression and poor survival." (PMID 35945203, 2022). "In addition, CD36 functions in tumor-associated immune cells, causing tumor intolerance and progression; thus, it has become a strategic target for cancer therapy." (PMID 36114448, 2022). "In addition, CD36-driven lipid metabolism reprogramming and the function of tumor-associated immune cells lead to tumor immune tolerance and tumorigenesis." (PMID 34234847, 2021). "Indeed, studies demonstrated that the upregulation of CD36 is associated either with tumor progression or tumor repression." (PMID 34063116, 2021). "Genetic deletion of CD36 could significantly hamper lipid uptake, accumulation, and oxidation, thus causing inhibition of tumour growth and tumour-infiltrating MDSC immunosuppressive function." (PMID 34685679, 2021). "Tumor-associated Tregs upregulate expression of CD36, an FA translocase." (PMID 33086598, 2020). "However, to date only one study has described the molecular mechanisms underlying the tumor-promoting effects of CD36 in GC." (PMID 33232276, 2020). "In tumor cells, CD36 associates with multiple ligands that influence the development of cancer." (PMID 31410189, 2019). "Furthermore, we found three lipid-metabolism related genes HMGCS2, GPX2 and CD36 associated with the tumor immune microenvironment were significantly correlated with prognosis." (PMID 31074374, 2019). "In particular, PPARγ, PTEN, and CD36 expression in F4/80-positive cells (red) was also markedly enhanced by apoptotic cell injection, which reflects apparent PPARγ, PTEN, and CD36 induction in tumor-associated macrophages (TAMs), as the F4/80-positive macrophage intensity was not different." (PMID 30842627, 2019). "Since in vitro silencing of CD36 significantly upregulated glycolysis, we therefore wanted to investigate whether inhibition of glycolytic targets could effectively inhibit tumor growth with CD36 deficiency in vivo." (PMID 31484922, 2019). "Moreover, CD36-driven lipid metabolic reprogramming and functions in tumor-associated immune cells lead to tumor immune tolerance and cancer development." (PMID 31410189, 2019). "Furthermore, we found that increased expression of CD36 in tumor tissues was positively associated with depth of tumor local invasion, lymph node metastasis, higher TNM stage and poor prognosis of GC patients." (PMID 30717785, 2019). "The expression level of CD36 in tumor tissues was positively associated with depth of local tumor invasion (P = 0.043) and higher TNM stage (P = 0.0019), but not with other clinico-pathological parameters including age, tumor differentiation degree and tumor size." (PMID 30717785, 2019). "CD36 is implicated in tumor metastasis through its roles in fatty acid metabolism." (PMID 29914089, 2018). "Our results also identified as relevant the expression of CD36, a protein reported to be critical for M2 macrophage activation, and PI3Kγ, which was recently reported to be involved in the immunomodulatory activity of tumor-associated myeloid subsets." (PMID 30179225, 2018). "Interestingly, this vessel density was comparable to that seen within the TME in tsp-1 (thrombospondin-1) knockout mice, which had deficient expression of TSP-1 (a ligand of CD36) and showed robust tumor angiogenesis." (PMID 28186980, 2017). "Whereas CD36 downregulation in the tumor endothelium is associated with malignant lesions of BC, which may partially explain the role of TSP-1 as a CD36 ligand in BC metastasis." (PMID 28186980, 2017). "In addition, clinically more aggressive tumours were associated with a greater degree of CD36 repression." (PMID 26784251, 2016).
tumor (continued). "CD36 has been implicated in the regulation of tumor angiogenesis." (PMID 24628875, 2014). "Additional work is required to elucidate the possible role tissue associated macrophages may play in CD36-HRG-TSP signaling as well as the anti-tumor properties of HRG in LL2 and B16F1 tumors." (PMID 22808089, 2012). "The association of CD36 with chemokines and their receptors highlights its role in chemokine-mediated immune cell recruitment, which aligns with established mechanisms of macrophage and monocyte recruitment and polarization within the tumor microenvironment (TME)." (PMID 41550652, 2025). "This elevated expression of CD36 in tumor-associated neutrophils may reflect an adaptive mechanism linked to tumor-cell interactions, such as lipid metabolism or immune suppression within the tumor microenvironment." (PMID 40549016, 2025). "In the case of CCA, when CD36 expression levels are elevated, lipid uptake is subsequently increased, and the increased lipid content in turn facilitates the survival of CSCs in the tumor microenvironment (TME), ultimately increasing the risk of recurrence in patients." (PMID 39984452, 2025). "However, CD36 expression was negatively correlated with tumor mutation burden in most cancer types." (PMID 34234847, 2021). "Interestingly, PKD-1 signaling appears to regulate tumor angiogenesis and is implicated in tumor arteriogenesis as it may regulate CD36 expression and vascular remodeling in the tumor microenvionment." (PMID 27200349, 2016). "These promote T cell functional exhaustion and underscore the therapeutic potential of blocking CD36 to boost anti‐tumor immunity." (PMID 41560416, 2026). "CD36 is involved in fatty acid metabolism and can act as a molecule in tumor cell reprogramming, and its abnormal expression can enhance the proliferation and survival ability of tumor cells." (PMID 41523911, 2026). "Recently, the interaction between PS and CD36 has been reported to be a crucial step in the fusion between monocytes and tumor cells." (PMID 39752516, 2025). "In this study, we report the reduced expression and tumor‐suppressive role of CD36 in TNBC development." (PMID 41267927, 2025). "In summary, CD36 is a multifunctional protein with key roles in lipid uptake, inflammation, immune regulation, angiogenesis, and tumor growth." (PMID 40565598, 2025). "Mechanistically, CD36 promoted uptake of OX-LDL into tumor infiltrating T cells and this induced lipid peroxidation as well as downstream activation of p38 mitogenic activation of protein kinase (MAPK)." (PMID 40855044, 2025). "In CRC, CD36 expression is significantly higher in tumor tissues compared to adjacent tissues, and CD36 expression is elevated in the liver and non-metastatic lesions." (PMID 40718481, 2025). "Tregs in the tumor microenvironment regulate metabolism by manipulating CD36-mediated uptake of free fatty acids and mTOR-mediated activity of amino acids pools such as serine via glutathione regulation." (PMID 40692789, 2025). "The fatty acid translocase CD36, which is frequently upregulated in various cancers, facilitates the uptake of long-chain fatty acids from the tumor microenvironment." (PMID 41350297, 2025). "It is now widely accepted that CD36 is overexpressed in a large variety of tumors and is involved in metastasis initiation, the proliferation of metastatic cells and tumor drug resistance." (PMID 39984452, 2025). "Given that CD36i mainly acts on CD36 on the cell membrane of tumor cells and immune cells, and that siSCD1 needs to enter tumor cells to perform gene silencing, we designed a multiresponsive core‐shell structured nanosystem, HA@CD36i‐TR@siSCD1." (PMID 39736148, 2025).